PTH (parathyroid hormone)
Diseases named in the same sentence as PTH in open-access papers (continued):
Sharing a sentence is not in itself a finding about the gene and the disease.
Hypocalcemia (continued). "It is important to note that postsurgical hypoparathyroidism (PTH-mediated) is the most common cause of hypocalcemia overall." (PMID 40225429, 2025). "The pathological hallmark of HP is insufficient secretion of parathyroid hormone (PTH), leading to hypocalcemia and associated clinical symptoms (e.g., limb paresthesia, muscle cramps, and osteoporosis)." (PMID 40979704, 2025). "Elevated serum phosphorus, along with 1,25-dihydroxyvitamin D (calcitriol) deficiency (due to loss of renal 1α-hydroxylase activity) and resultant hypocalcemia, triggers increased PTH synthesis and parathyroid cell proliferation." (PMID 40725638, 2025). "Hypoparathyroidism is a rare endocrine disorder characterized by hypocalcemia and hyperphosphatemia caused by insufficient parathyroid hormone (PTH)." (PMID 40655406, 2025). "Serum calcium levels in the human body are primarily regulated by PTH and vitamin D. Since PTH serves as the primary biochemical marker for assessing serum calcium, it has been extensively investigated as a potential risk factor for hypocalcemia after TT." (PMID 40786097, 2025). "Hypocalcemia, vitamin D deficiency, and excessive secretion of parathyroid hormone (PTH) caused by hypocalcemia contribute to decreased raw materials for bone formation, increased bone resorption, and raised risk of OP and osteoporotic fractures." (PMID 39949568, 2025). "The biochemical parameters of mineral bone disorders including increased fibroblast growth factor 23 (FGF23), hyperphosphatemia, hypocalcemia, elevated parathormone (PTH), and 1,25-dihydroxy vitamin D3 deficiency, were frequently observed in CKD." (PMID 40421989, 2025). "Severe hypocalcemia results from an increased influx of calcium into the bone due to the sudden removal of high levels of PTH, causing bone resorption." (PMID 40342445, 2025). "Autoantibodies against CaSR can act as functional receptor agonists, directly inhibiting PTH secretion and causing hypocalcemia." (PMID 41465179, 2025). "In SHPT, disrupted mineral metabolism (phosphate retention, vitamin D deficiency, and hypocalcemia due to renal failure) triggers compensatory parathyroid hyperplasia and excessive parathyroid hormone (PTH) release, driving abnormally high bone turnover." (PMID 41227247, 2025). "In agreement with our findings, higher preoperative PTH levels were shown to be statistically significantly associated with the development of hypocalcemia." (PMID 40517023, 2025). "It was postulated that transitory tissue deposition caused hypocalcemia and hypoparathyroidism, characterized by elevated serum phosphorus and abnormal PTH levels." (PMID 40291321, 2025). "The hypomagnesemia gave a clue to the leading cause of the refractory hypocalcemia, with PTH impaired secretion and resistance from hypomagnesemia." (PMID 40492015, 2025). "After parathyroidectomy, there is a significant disconnect between the processes of bone formation and resorption, which is affected by a rapid decrease in PTH and high levels of alkaline phosphatase, which increases the risk of hypocalcemia." (PMID 39941666, 2025). "Both ADH1 and ADH2 are associated with hypocalcemia and normal or inappropriately low levels of circulating PTH." (PMID 39658204, 2025). "Our study identified higher preoperative ALP, lower pre‐operative corrected calcium, higher pre‐operative PTH levels, and younger age as risk factors for postoperative hypocalcemia." (PMID 40517023, 2025). "Seven homozygous non-lethal PTH1R mutations were recently described in patients with various degrees of delayed ossification and PFTE, associated with PTH-resistant hypocalcemia in some cases." (PMID 40904804, 2025). "Outcomes, including all-cause mortality, MACEs, fractures, hypocalcemia, and PTH suppression (≤300 pg/mL), were compared between groups over a 3-year follow-up." (PMID 40362848, 2025).
Hypocalcemia (continued). "As a rule, the development of changes in bone tissue in children correlates with the progression of CKD, which is associated with impaired parathyroid hormone production, hypocalcaemia, hypophosphatemia, and metabolic acidosis." (PMID 40363983, 2025). "HypoPTH is a rare disorder characterized by deficient production or biological activity of PTH that results in hypocalcemia and hyperphosphatemia." (PMID 40177730, 2025). "First, mutations in calcium-sensing receptors (CASR) can suppress PTH levels and exert a hypercalciuric hypocalcemia condition." (PMID 40000975, 2025). "CKD causes a defect in the activation of vitamin D in the kidneys, which causes hypocalcemia and hyperphosphatemia, which results in a compensatory increase in parathyroid gland cellularity and parathyroid hormone synthesis, which in turn causes SHPT." (PMID 39791168, 2025). "Regarding postoperative HypoPTH, this is a clinical disorder caused by a deficiency of parathyroid hormone (PTH) following thyroid surgery, biochemically characterized by hypocalcemia and hyperphosphatemia." (PMID 41515984, 2025). "Chronic hypoparathyroidism (HypoPT) is a rare endocrine disorder characterized by hypocalcemia and hyperphosphatemia, due to persistent absence or severe deficiency of parathyroid hormone (PTH)." (PMID 40702385, 2025). "Our case demonstrates this rare but clinically significant link and highlights the need for further investigation into the interplay between vitamin D deficiency, hypocalcaemia, elevated parathyroid hormone levels, and hypertension." (PMID 41257110, 2025). "The effect of imatinib on calcium normalization was confounded by denosumab, which can cause hypocalcemia and transient PTH changes." (PMID 41479802, 2025). "One of the most important factors underlying hypocalcemia in hypomagnesemia conditions is the impaired secretion of parathyroid hormone (PTH), referred to as paradoxical hypoparathyroidism." (PMID 40740723, 2025). "Many studies have shown that female gender is a risk factor for postoperative transient hypocalcemia development, and the effects of hormonal changes on vitamin D, PTH, and calcium absorption have been emphasized." (PMID 40433414, 2025). "Three PTH1R mutations found in patients with symptomatic hypocalcemia and PTH resistance map to the receptor TM1 (R186H) and TM2 (D241E and I237N)." (PMID 40904804, 2025). "Vitamin D deficiency increases PTH both by reducing the intestinal absorption of Ca2+ and, thus, causing hypocalcemia and, to a lesser extent because the inhibitory action of calcitriol on PTH production is lost." (PMID 40183914, 2025). "Phosphate then bound to calcium in the blood, forming calcium phosphate, which caused hypocalcemia and further stimulated PTH secretion." (PMID 39866529, 2025). "The diagnostic approach to hypocalcemia should begin with confirming calcium levels; correcting for albumin; and measuring PTH, phosphate, and serum magnesium." (PMID 40492015, 2025). "In the absence of confirmatory genetic testing, like in this case, other potential causes of hypocalcemia with elevated PTH must be considered." (PMID 41322012, 2025). "In this report, we describe a family with a very rare mechanism of familial hypocalcemia due to a PTH mutation." (PMID 39435356, 2024). "Hyperphosphatemia, deficient calcitriol levels, and hypocalcemia increase PTH production and secretion." (PMID 39697967, 2024). "Postoperatively, she manifested severe hypocalcemia and vitamin D deficiency alongside elevated PTH levels." (PMID 39478762, 2024). "In the PTH >10 pg/mL group, the decrease in 1,25(OH)2D levels was significantly associated with postoperative hypocalcemia (p<0.05)." (PMID 38803480, 2024).
Hypocalcemia (continued). "The most common cause of postoperative hypocalcemia after PTX is impaired parathyroid blood supply characterized by low PTH, whereas HBS characterized by elevated PTH and increased bone formation is not so common." (PMID 39312325, 2024). "Hungry bone syndrome (HBS) is commonly defined as severe and prolonged postoperative hypocalcemia caused by a sudden decrease in parathyroid hormone (PTH) levels after PTX." (PMID 39152506, 2024). "Four factors were found to be significantly associated with postoperative hypocalcemia: Lymph node metastasis (P = 0.049, OR = 2.6), total thyroidectomy (P = 0.001, OR = 8.0), 25(OH)D3 level (P = 0.0005), and PTH level (P < 0.001, OR = 12.6)." (PMID 40071247, 2024). "In adults, VDD rarely causes severe hypocalcemia due to the regulatory role of parathyroid hormone (PTH); however, in rapidly growing infants and children, VDD can lead to severe hypocalcemia and even seizures because their higher calcium demands are unmet." (PMID 39350885, 2024). "Administration of intravenous Ca to recumbent cows with clinical hypocalcemia also causes a reduction in PTH, as blood Ca rises to a concentration that reduces the secretion of PTH." (PMID 38646577, 2024). "Parathyroid gland cells are directly stimulated by hyperphosphatemia, which causes nodular hyperplasia and increased PTH release, leading to persistent hypocalcemia." (PMID 39152506, 2024). "Various factors contribute to the risk of post-thyroidectomy hypocalcemia, including perioperative parathyroid hormone (PTH) levels, preoperative vitamin D (VD) deficiency, and potential parathyroid gland damage or removal during surgery." (PMID 38803480, 2024). "The hypocalcemia can be explained by inadequately low parathyroid hormone (PTH) levels, caused by a hypomagnesemia-induced reduction in PTH production and secretion." (PMID 39099563, 2024). "Gastric acid suppression reduces the absorption of calcium and magnesium ions from the gastrointestinal tract and causes hypomagnesemia and hypocalcemia that consequently increases serum PTH secretion." (PMID 38234669, 2024). "The study indicated that tPTX+AT, relative to sPTX, enhances the long-term control of elevated parathyroid hormone levels and helps in preventing disease recurrence, albeit with a higher risk of long-term hypocalcemia." (PMID 39931436, 2024). "The risk of hypocalcemia after total thyroidectomy was also studied by grouping patients according to their PTH levels." (PMID 38803480, 2024). "Hypocalcemia, and hypophosphatemia are associated with low Vitamin D3 and parathyroid hormone but high calcitonin." (PMID 39492784, 2024). "Laboratory studies confirmed severe hypocalcemia, low parathyroid hormone (PTH), and deficiencies in fat-soluble vitamins, complicating her clinical management." (PMID 39411620, 2024). "Previous studies have demonstrated that pseudohypoparathyroidism caused by hypocalcemia and hyperphosphatemia is due to the resistance of the primary target organ to PTH." (PMID 38731279, 2024). "A subsequent study described a 24-year old girl who also presented with neonatal hypocalcemia and seizure and found to have undetectable PTH due to a mutation at codon 23 of the preproPTH leading to inefficient processing of the prehormone." (PMID 39435356, 2024). "Measuring serum parathormone (PTH) post-thyroidectomy is a sensitive method for identifying patients at risk for hypocalcaemia." (PMID 39649119, 2024). "Pseudohypoparathyroidism is characterized by the inability of renal epithelial cells at the proximal renal tubule to respond to PTH, causing excess hormone secretion accompanied by hypocalcemia and hyperphosphatemia." (PMID 38929327, 2024). "This led to their misdiagnosis of PHPT type 1b for many years before WES disclosed the underlying PTH mutation, which caused hypocalcemia and secondary hyperparathyroidism of biologically inactive PTH." (PMID 39435356, 2024).
Hypocalcemia (continued). "Patients undergoing total thyroidectomy or parathyroidectomy who have eight-hour postoperative PTH levels less than 15 pg/mL (1.6 pmol/L) are at a very high risk of developing postoperative hypocalcemia." (PMID 39258042, 2024). "SHPT is diagnosed by biochemical abnormalities characterised by elevated levels of PTH, often accompanied by hyperphosphataemia, hypocalcaemia and vitamin D deficiency." (PMID 39208984, 2024). "Virus-dependent calcium influx into cells, vitamin D deficiency, functional hypoparathyroidism, and PTH resistance are considered causes of hypocalcemia in COVID-19." (PMID 39262524, 2024). "In order to prevent the occurrence of hypocalcemia caused by denosumab, predose assessment, including baseline calcium, PTH, renal function, and vitamin D levels, should be performed prior to treatment, which will help identify higher risk groups." (PMID 39287282, 2024). "Chronic kidney disease (CKD) patients are at risk of secondary hyperparathyroidism (HPT-II) due to high PTH levels and various metabolic disturbances, such as calcitriol deficiency, hypocalcemia, and hyperphosphatemia." (PMID 39152506, 2024). "Given the patient’s hypocalcemia with normal PTH levels, renal function, and vitamin D levels, COVID-19 was considered the cause of hypocalcemia." (PMID 39262524, 2024). "Elevated levels of parathyroid hormone predispose patients to hyperphosphatemia, and concurrent deficiencies in active vitamin D, anemia, and hypocalcemia contribute to the hyperplasia and hypertrophy of the parathyroid gland." (PMID 39130819, 2024). "Hungry bone syndrome (HBS) is defined as prolonged hypocalcemia caused by a sudden decrease in parathyroid hormone (PTH) levels after parathyroidectomy (PTX)." (PMID 39152506, 2024). "Pseudohypoparathyroidism (PHP), characterized by resistance to PTH, is a rare cause of hypocalcemia." (PMID 39350885, 2024). "1,25(OH)2D plays an important role in preventing sudden, severe hypocalcemia due to decreased PTH levels after total thyroidectomy, whereas high preoperative 1,25(OH)2D levels are a significant risk factor for postoperative hypocalcemia." (PMID 38803480, 2024). "In contrast, in secondary hyperparathyroidism, the PTH elevation is caused by an external stimulus that causes hypocalcemia." (PMID 39408619, 2024). "Studies have suggested that long-term EDTA chelation with increased calcium loss from the body can cause hypocalcemia and increased release of parathyroid hormone (PTH), which is a well-known cause of bone loss and osteoporosis." (PMID 38137375, 2023). "After this report, a few years later, Piranavan and colleauges described another case of severe hypocalcemia (5.8 mg/dL) associated with low PTH (7.77 pg/mL) in a 61-year-old female patient treated with nivolumab for metastatic small cell lung cancer." (PMID 36672478, 2023). "Patients with PHP1B manifest varying degrees of PTH-resistant hypocalcemia attributed to distinct genetic mutations associated with the condition." (PMID 38137593, 2023). "PTH evaluated in the postoperative period has been frequently associated with the prediction of hypocalcemia after TT." (PMID 36651710, 2023). "In one case, hypocalcemia has been associated with undetectable PTH levels, suggesting direct damage to the parathyroid glands that required long-term treatment with calcium plus vitamin D." (PMID 36672478, 2023). "Severe hypocalcemia, hypophosphatemia, and hypomagnesemia are associated with reduced levels of parathyroid hormone (PTH)." (PMID 37233634, 2023). "When hypocalcemia is associated with low levels of PTH, in addition to oral calcium supplementation, it is also necessary to administer calcitriol at a variable dosage from 0.25 to 0.5 mcg, once or twice a day." (PMID 37198359, 2023).
Hypocalcemia (continued). "According to the American Thyroid Association, in most studies, the timing of PTH measurements has ranged from 10 min to 24 h post-thyroidectomy, and a postoperative PTH level of <15 pg/mL is usually predictive of hypocalcemia." (PMID 36902740, 2023). "It is caused by hypocalcemia, hyperphosphoremia, or vitamin D deficiency, and leads to increased PTH synthesis and the proliferation of parathyroid cells." (PMID 37713846, 2023). "On the contrary, postoperative hypocalcemia associated with normal (or high, but lower than the preoperative level) PTH, as described in hungry bone syndrome, was reported in a few cases/series." (PMID 37893182, 2023). "Hypocalcemia due to an abnormal PTH, i.e., isolated hypoparathyroidism (IHP), can be caused by homozygous or heterozygous mutations in the PTH gene itself." (PMID 36795755, 2023). "Low Mg levels stimulate PTH secretion, while very low serum Mg concentrations induce a paradoxical blockage, resulting in clinically relevant hypocalcemia in severely Mg-deficient patients." (PMID 37446123, 2023). "These patients displayed renal resistance to PTH and consecutive hypocalcemia, which further enhances a theoretical risk of tertiary HPT (that is actually exceptionally described) in association with PT excess-induced bone disease." (PMID 37296804, 2023). "The activation of CaSR by autoantibodies cause reduced PTH secretion and hypocalcemia, with similar mechanisms reported for the calcimimetic drug cinacalcet." (PMID 36672478, 2023). "PTH is elevated in CKD due to hypocalcaemia caused by impaired vitamin D activity and phosphate retention when the renal function is reduced." (PMID 37102048, 2023). "The findings related to the S1-to-P1 change seem opposite to those observed for three siblings and a recently described unrelated patient, who presented with severe hypocalcemia due to a homozygous [R25C]PTH mutation." (PMID 36795755, 2023). "Existing literature supports the association between hypomagnesemia and hypocalcemia, where low Mg concentrations are believed to impact the release of parathyroid hormone, contributing to a state of hypocalcemia." (PMID 37829115, 2023). "The higher baseline preoperative PTH levels possibly reduced the risk of postoperative hypocalcemia, especially among those patients with higher PTH levels above the mean level of 40.21 pg/ml in the perioperative group." (PMID 37288589, 2023). "The short half-life of parathyroid hormone is 3–5 min which easily predisposes patients to hypocalcemia." (PMID 37636752, 2023). "We now determined the mechanism through which hypocalcemia develops in patients with this homozygous variant despite an appropriate increase in PTH secretion." (PMID 36795755, 2023). "Because of the elevated PTH levels in response to the severe hypocalcemia, a PHP variant was initially considered as the underlying diagnosis." (PMID 36795755, 2023). "Critical care patients who are infused with ionic calcium during arterial blood gas evaluation are at risk of hypocalcaemia, which affects intact parathyroid hormone (iPTH) tests." (PMID 37241010, 2023). "The American Thyroid Association indicates low postoperative PTH as a predictor of post-total thyroidectomy hypocalcemia." (PMID 34564834, 2022). "The 4-h PTH to pre-surgery PTH ratio was the most accurate (90.81%) and the most specific (94.37%) test to identify patients at risk of developing symptomatic hypocalcemia." (PMID 35566513, 2022). "Postoperative PTH levels have been reported by numerous studies to be reliable early predictors of patients at low risk of hypocalcaemia, who are hence suitable for early discharge." (PMID 35247092, 2022). "Intraoperative bruising, devascularisation or inadvertent excision of the parathyroid glands during neck surgery can result in low levels of parathyroid hormone (PTH) causing hypoparathyroidism and hypocalcaemia." (PMID 36184675, 2022).